CHAT (choline O-acetyltransferase)
Diseases named in the same sentence as CHAT in open-access papers (continued):
Sharing a sentence is not in itself a finding about the gene and the disease.
neuroblastoma (6 papers, 2012 to 2025). Neuroblastoma (NB) is the most common solid, extracranial childhood tumor. "The findings in this manuscript demonstrate that 82-kDa ChAT aggregates in nuclei of neural cells and associates with chromatin at gene promoters and exons after human neuroblastoma SH-SY5Y cells are exposed to oligomeric Aβ1–42." (PMID 27052102, 2016). "To further investigate the observed phenomenon, we performed cell surface confocal microscopy targeting ChAT in the same SH-SY5Y neuroblastoma cell line." (PMID 41226363, 2025). "The discovery of extracellular membrane-bound ChAT uniquely in neuroblastoma SH-SY5Y cells points to a novel form of in situ ACh signaling that warrants further investigation." (PMID 41226363, 2025). "These spheroids are differentiated into mature neurons (MAP2-positive) and cholinergic neurons (ChAT-positive) from human neuroblastoma cells." (PMID 40711147, 2025). "In summary, this study provides compelling evidence for the presence of an extracellular, membrane-bound form of ChAT exclusively in neuroblastoma cells, in contrast to the three lung cancer cell lines tested." (PMID 41226363, 2025). "In this study, we investigated the expression of ChAT and related cholinergic markers in four human tumor cell lines: neuroblastoma (SH-SY5Y), lung adenocarcinoma (A549), and two small cell lung cancer lines (H69 and H82)." (PMID 41226363, 2025). "We developed an in vitro model to measure both extracellular and intracellular ACh levels using the human cholinergic neuroblastoma cell line, LA-N-2, which have been reported to express Ch transporter, ChAT, muscarinic ACh receptor (mAChR), and AChE." (PMID 34637466, 2021). "We studied a possible role for exosomes in neuronal differentiation using N18TG2 parental neuroblastoma cells and a clone of N18TG2 transfected with cDNA encoding choline acetyltransferase (2/4 ChAT)." (PMID 26082068, 2012). "Interestingly, among the four examined cell lines, only the SH-SY5Y neuroblastoma cells exhibited surface ChAT expression." (PMID 41226363, 2025). "Notably, the identification of an extracellular, membrane-bound form of ChAT uniquely in neuroblastoma SH-SY5Y cells reveals a previously unrecognized mode of in situ ACh signaling." (PMID 41226363, 2025). "Also, transfection of ChAT cDNA in the neuroblastoma cell N18TG2 lead to increased capacity of the cell to grow fibers, express synapsin 1, and induced neurites with carbachol treatment." (PMID 30687846, 2018). "Therefore, the distinct extracellular localization of ChAT in the SH-SY5Y neuroblastoma cell line may represent a novel physiologically relevant cholinergic-enhancing mechanism, potentially involving rapid in situ synaptic recycling of ACh and prolonging its action at the synapse." (PMID 41226363, 2025). "The small cell lung carcinoma (SCLC) cell lines H69 and H82, the lung adenocarcinoma cell line A549, and the neuroblastoma cell line SH-SY5Y were evaluated for ChAT cell surface expression without fixation or permeabilization." (PMID 41226363, 2025). "Interestingly, under these conditions, surface ChAT localization was exclusively detected in the SH-SY5Y neuroblastoma cell line, but not in the other cell lines." (PMID 41226363, 2025).
viral infection (6 papers, 2016 to 2024). "At 3 weeks post-viral infection, we performed double immunocytochemistry with anti-ChAT and anti-tdTomato antibodies on the brain sections and found that the DMV displayed a small number of tdTomato-positive cells." (PMID 39436946, 2024). "Research has revealed a genetic proof-of-function for choline acetyltransferase (ChAT) in T cells during viral infection and identified a pathway of T-cell migration that sustains antiviral immunity." (PMID 34045460, 2021). "At later stages, such as 6–8 weeks post viral infection (wpi), reprogrammed neurons expressed high levels of choline acetyltransferase (CHAT), the mature MN marker." (PMID 32317929, 2020). "One obvious distinction between expression of ChR2 driven via the Ai32 reporter line and via viral infection is the duration of expression: in ChAT-Cre/Ai32(ChR2-YFP) mice, expression is prolonged and likely occurs throughout development." (PMID 27243816, 2016).
colitis (5 papers, 2015 to 2025). Inflammation of the colon. "In relation to the CTCF analyses, the reduction observed in GPR41-ir and ChAT-ir neurons in the Colitis group is consistent with the loss of these same neurons in this group." (PMID 37443707, 2023). "In a mouse model of colitis induced by dextran sulfate sodium (DSS), the ablation of choline acetyltransferase-positive (ChAT+) neurons aggravated colitis and resulted in motor dysfunction." (PMID 41305570, 2025). "Quantitative results demonstrated losses of nNOS-ir, ChAT-ir, and GPR41-ir neurons in the Colitis group and Butyrate treatment attenuated neuronal loss." (PMID 37443707, 2023). "An increase in the total number of nNOS neurons, as well as a decrease in the number of ChAT neurons was revealed 72 hours after the induction of colitis." (PMID 28420434, 2017). "Our study revealed an increase in the number of nNOS neurons, as well a decrease in the number of ChAT neurons at 24 hours after induction of colitis." (PMID 26397368, 2015). "The number of ChAT-ir neurons per ganglion showed a reduction of 28.3% in the Colitis group (6.1 ± 0.1) when compared to the Sham group (8.6 ± 0.1; p < 0.0001) and an increase of 26.2% in the Butyrate group (8.4 ± 0.1; p < 0.0001), compared to the Colitis group." (PMID 37443707, 2023). "On the other hand, the reduction in the total area of ChAT-ir neurons in the Colitis group suggests that, at least in the TNBS protocol and with an interval of 7 days after acid injection, enteric neurons may be affected differently by intestinal inflammation." (PMID 37443707, 2023). "However, the possible regulation of ERβ on plectin, ELOVL1, and ChAT in colitis still needs more animal model experiments and clinical studies to investigate." (PMID 37569842, 2023). "The quantitative analysis identified a reduction in the number of nNOS-ir, ChAT-ir, and GPR41-ir neurons in the Colitis group when compared to the Sham group." (PMID 37443707, 2023). "Myenteric ChAT-ir neurons showed a reduction in CTCF of 21.0% in the Colitis group (1,530,379 ± 52,098) when compared to the Sham group (1,937,090 ± 53,896; p < 0.001) and an increase of 21.3% in the Butyrate group (1,944,830 ± 53,965) when compared to the Colitis group (p < 0.001)." (PMID 37443707, 2023).
colon cancer (5 papers, 2011 to 2024). "Although studies examining the role of M3R and α7nAChR in cancer have been relatively studied, there are limited studies identifying the role of ChAT in colon cancer progression." (PMID 37828429, 2023). "ChAT itself is overexpressed in colon cancer cells compared to normal mucosa, while ChAT immunoreactive tuft cells are found throughout the gastrointestinal tract." (PMID 34203220, 2021). "Quantitative real-time PCR and immunostaining provided evidence of ChAT expression in both human colon cancer cells and colon cancer tissue specimens, and treatment of human colon cancer cells with acetylcholinesterase inhibitors increased their proliferation in vitro." (PMID 38791353, 2024). "ChAT was found to be overexpressed in colon cancer specimens compared to normal colon samples." (PMID 37828429, 2023). "High ChAT is noted in cytoplasmic localization of H508 and Caco-5 colon cancer cells." (PMID 37828429, 2023). "Using quantitative real-time PCR, our group demonstrated that H508, WiDr, and Caco-2 human colon cancer cell lines all express ChAT, that H508 and Caco-2 cells release ACh into cell culture media, and that muscarinic receptor antagonists inhibit proliferation of unstimulated H508 cells by about 40%." (PMID 24212649, 2011). "Immunohistochemical staining of surgical specimens revealed that normal colonic epithelium has weak or no staining for ChAT, whereas half of the colon cancer specimens examined exhibited moderate to strong staining." (PMID 24212649, 2011).
lung carcinoma (5 papers, 2015 to 2025). "It is reasonable to consider that the increased mRNA and protein expression of ChAT was associated with the high expression of nAChR in lung cancer cells." (PMID 25591716, 2015). "Data suggested that lung cancer had different systems to increase the production of ACh, such as upregulation of ChAT and VAChT, or downregulation of acetylcholinesterase (AChE)." (PMID 35565451, 2022). "The cholinergic system comprising ACh and its synthesizing enzyme, choline acetyltransferase (ChAT), as well as its degrading enzyme, acetylcholinesterase (AChE), have been detected in several cancer entities, such as colon, liver and lung cancer." (PMID 33357230, 2020). "Intriguingly in this context, recent studies have shown a very critical role of ChAT in promoting cancer cell proliferation in both colon and lung cancer." (PMID 29176551, 2017). "The present study was designed to determine the expression of ChAT and ChoK in order to clarify the roles of phosphorylation and acetylation pathways in 11C-Choline metabolism in different types of lung cancer." (PMID 25591716, 2015). "Reverse transcription polymerase chain reaction and western blotting were used to investigate the expression of choline acetyltransferase (ChAT) and choline kinase α (ChoK) in lung cancer tissue and normal lung tissue." (PMID 25591716, 2015). "In addition, squamous cell carcinoma of the lung tumors expressed ChAT, suggesting a role of the cholinergic system in the progression of lung cancers." (PMID 35565451, 2022). "In addition, 60% of all the squamous cell carcinoma of the lung (SCC-L) tumors expressed ChAT, suggesting a role of the cholinergic system in the progression of lung cancers." (PMID 35565451, 2022).
myocardial infarction (5 papers, 2012 to 2024). Gross necrosis of the myocardium, as a result of interruption of the blood supply to the area, as in coronary thrombosis. "Experimental studies on mice have shown that ChAT (key enzyme for acetylcholine synthesis) gene silencing (mice ChAT/- knockout) in adrenergic neurons reduced myocardial infarction." (PMID 36798942, 2023). "Further, reduction of ChAT expression observed in the pedunculopontine nucleus (Ch5) of a rat model of myocardial infarction was accompanied by diminished REM sleep." (PMID 25405505, 2014). "Therefore, ChAT tg mice with myocardial infarction (MI) survived more than WT mice in the chronic phase, with a survival rate of 92.3% (two weeks after the onset of infarction)." (PMID 33430415, 2021). "However, pretreating IR-treated mice with the ChAT inhibitor HC-3 before IR removed this myocardial infarction sparing effect, as the ratio of the infarcted area returned to a level comparable with that of the control mice at 0.56±0.03 (vs. IR; P<0.05, n = 7)." (PMID 23209825, 2012).
Obesity (5 papers, 2019 to 2025). Accumulation of substantial excess body fat. "ChAT was undetectable in all healthy subjects (n = 10), whereas it was detected in 10 of the 31 subjects with obesity." (PMID 38141849, 2024).
amyotrophic lateral sclerosis (4 papers, 2015 to 2024). Amyotrophic lateral sclerosis (ALS) is a neurodegenerative disease characterized by progressive muscular paralysis reflecting degeneration of motor neurons in the primary motor cortex, corticospinal tracts, brainstem and spinal cord. "For example, diminished activity of ChAT, observed in the SC of patients with Amyotrophic lateral sclerosis (ALS), was supposed to be implicated in MN loss-of-function." (PMID 37963881, 2023).
Cerebral ischemia (3 papers, 2011 to 2017). Restriction of arterial blood supply to the brain associated with insufficient oxygenation to support the metabolic requirements of the tissue. "Cerebral ischemia has also been correlated with the degree of loss of cholinergic neurons, including the levels of acetylcholine (ACh) and choline acetyltransferase (ChAT)." (PMID 19395577, 2011). "We confirmed that LA treatment in the MCAO-induced cerebral ischemia model rat improved spatial learning and memory and restored ChAT activity in the CA1 region." (PMID 28408940, 2017). "In patients with cerebral ischemia, the lesions are located in the hippocampus and cortex where the activity of ChAT increases, while the activity of AChE decreases." (PMID 27293454, 2016). "The present results demonstrated that focal cerebral ischemia induced by middle cerebral artery occlusion (MCAO) produced severe deficits in performance on the Morris water maze along with signs of neurodegeneration, including decreased ChAT and AChE activity in the hippocampus." (PMID 19395577, 2011).
Hyperglycemia (3 papers, 2017 to 2025). An increased concentration of glucose in the blood. "Our results showed that the ratio of TH and ChAT was imbalanced in hyperglycemia, indicating that both the sympathetic and vagus nerves were impaired during T2DM." (PMID 40380290, 2025). "We presumed here that hyperglycemia might abate InsR and IGF-1R expressions in the myenteric ChAT+ neurones but the detailed mechanism needs to be further clarified." (PMID 28931726, 2017).
Hypertension (3 papers, 2022 to 2024). The presence of chronic increased pressure in the systemic arterial system. "In mice with angiotensin II-induced hypertension, systemic administration of recombinant ChAT substantially reduced the mean arterial blood pressure." (PMID 38812748, 2024). "Our group also evaluated the ChAT mRNA expression following hypertension and treatment with captopril and losartan." (PMID 35528844, 2022). "Similarly, the genetic ablation of ChAT in ChAT-positive T cells results in hypertension in mice, which is attributed to an endothelium-eNOS-dependent mechanism." (PMID 38812748, 2024). "In the NTS, genes encoding CHAT, the enzyme that synthesizes acetylcholine, as well choline and acetylcholine transporters CHT and VACHT, respectively, showed notable downregulation early in hypertension development, at 8 wk of age, and at the extended chronic stage at 24 wk." (PMID 38145287, 2024). "We assessed whether the expression levels of ACE, ChAT, AT1, and AT2 in hippocampus tissue were affected by hypertension in adult rats." (PMID 35528844, 2022).
sudden infant death syndrome (3 papers, 2018 to 2023). Unexpected death in infancy which remains unexplained following autopsy, review of the medical history, and investigation of the death circumstances and death scene. "Furthermore, in cases of sudden infant death syndrome, decreased activity of ChAT has been demonstrated in the CNS." (PMID 29189923, 2018).
tauopathy (3 papers, 2017 to 2024). Neurodegenerative disorders involving deposition of abnormal tau protein isoforms (tau proteins) in neurons and glial cells in the brain. "The distribution of both argyrophil tangle‐like structures and phosphorylated tau coincided with the progression of axonal swellings, especially at 72 hrs, which indicated that ChAT transport impairment might be due to these tauopathies." (PMID 28656644, 2017). "The accumulation of pathologic protein aggregates in BF such as tauopathy and amyloid ß aggregates are likely the targets of an immune response including ChAT+ cells colocalized with pathology Tau though seems not abundant." (PMID 38978722, 2024). "However, the colocalizations of tauopathy with ChAT+ cells were not particularly abundant." (PMID 38978722, 2024).
Thiamine deficiency (3 papers, 2018 to 2020). Thiamine deficiency is a condition that occurs due to not enough thiamine (vitamin B1). "Thiamine deficiency (TD) also reduces activity of choline acetyltransferase (ChAT) which will cause the decrease of acetylcholine; TD also induces excess glutamate release, both of these are important pathogenesis for dementia." (PMID 32755028, 2020). "In line with our observations, Hall and Savage reported that wheel running restored the loss of ChAT+IR neurons in a rodent model of thiamine deficiency-induced neurodegeneration." (PMID 30296276, 2018). "Previous studies have found that voluntary exercise can reverse ChAT+IR neurodegeneration in a rodent thiamine deficiency model prompting an investigation of AIE combined with wheel running." (PMID 30296276, 2018). "Similarly, fimbria/fornix transection and thiamine deficiency has been reported to reduce the somal size of surviving ChAT+IR neurons." (PMID 30296276, 2018).
ulcerative colitis (3 papers, 2021 to 2023). An inflammatory bowel disease involving the mucosal surface of the large intestine and rectum. "ACh is a key regulator of epithelial tightness in the proximal colon, and in patients with ulcerative colitis, ChAT expression is reduced in endocrine and epithelial cells of the mucosa." (PMID 37569842, 2023). "In contrast, epithelial cells of ulcerative colitis patients displayed downregulation of ChAT, indicating, ChAT has differential involvement in different diseases affecting epithelial linings and smooth muscles." (PMID 33936095, 2021).
amnesia (2 papers, 2016). Pathologic partial or complete loss of the ability to recall past experiences ( AMNESIA, RETROGRADE) or to form new memories ( AMNESIA, ANTEROGRADE). "Both Rb1 and Rg1 have been shown to improve the scopolamine-induced amnesia in rodents and also elevate the level of choline acetyltransferase (ChAT) in rodent brains." (PMID 27630732, 2016). "Therefore, protecting cholinergic system from functional degeneration and sustaining the normal activity of ChAT and AChE might be serviceable against SCOP-induced amnesia." (PMID 27556046, 2016).
amyloid (2 papers, 2014 to 2022). "Brain pathology associated with AD was also impacted by long-term exercise including significant reductions in amyloid load, microgliosis, and preservation of ChAT+ cells (cholinergic function) in the brain of APPNL-G-F mice." (PMID 36180883, 2022).
autism (2 papers, 2021 to 2023). Persistent deficits in social interaction and communication and interaction as well as a markedly restricted repertoire of activity and interest as well as repetitive patterns of behavior. "Monoallelic Cul3 ablation in ChAT+ neurons recapitulated social preference deficits similar to those seen in mice with Cul3 deficiency in forebrain glutamatergic neurons and other Cul3 models of autism." (PMID 36693858, 2023). "Here, we developed a new mouse that relies on ChAT+ cell-specific Cul3 deletion and studied the differential contribution of cholinergic neurons in the BF and STR to autism-associated behaviors and cognition." (PMID 36693858, 2023).
Brain atrophy (2 papers, 2019 to 2023). Partial or complete wasting (loss) of brain tissue that was once present. "Notably, F3.ChAT cells recovered the microvessel density in the muscles of aged rats, leading to an increase in muscle mass as well as attenuation of brain atrophy." (PMID 38067139, 2023).
breast carcinoma (2 papers, 2020 to 2023). "The expression of ChAT in lung tissues from breast cancer patients with lung metastasis was significantly higher than that in patients with non-tumor pulmonary diseases." (PMID 37773152, 2023). "More importantly, the expression of ChAT in lung tissues from breast cancer patients with lung metastasis is profoundly higher than that in lungs of patients with non-tumor pulmonary diseases." (PMID 37773152, 2023). "The parasympathetic innervation has been demonstrated in gastric, prostate and breast cancers using choline acetyltransferase (ChaT) or vesicular acetylcholine transporter (VAchT) as specific markers." (PMID 32477953, 2020). "The expression of ChAT in lung tissues from breast cancer patients with lung metastasis and from patients with non-tumor bearing pulmonary diseases was examined by immunohistochemistry." (PMID 37773152, 2023). "Breast cancer patients with lung metastasis showed significantly increased expression of ChAT in their lungs than did patients with non-tumor pulmonary diseases." (PMID 37773152, 2023).